MEST (mesoderm specific transcript)
Description:
Plays an important role in enabling neurons to transition from bipolar to multipolar shapes, a process essential for their correct migration toward the cortical plate during brain development. This function is likely achieved through the regulation of N-cadherin-dependent cell adhesion and the modulation of Akt and canonical Wnt signaling pathways. Essential for the development and maintenance of meso-diencephalic dopaminergic (mdDA) neurons during development. Negatively regulates the canonical Wnt signaling pathway during adipogenic differentiation by reducing the glycosylation, maturation, and cell membrane localization of the Wnt coreceptor LRP6.
Synonyms: PEG1
Tractability: Antibody: UniProt predicts a signal peptide or a membrane-spanning region. PROTAC: its protein half-life has been measured.
Target class: Enzyme; Hydrolase
Gene: Protein-coding gene on chromosome 7 (130,486,171 to 130,506,465, forward strand). Ensembl gene ENSG00000106484.
Subcellular location: Endoplasmic reticulum membrane
Subcellular location (Human Protein Atlas): Cytosol; Golgi apparatus
Gene Ontology:
Molecular function: protein binding; catalytic activity
Biological process: fat cell differentiation; mesoderm development; negative regulation of canonical Wnt signaling pathway; negative regulation of glycoprotein biosynthetic process; negative regulation of protein localization to plasma membrane; neuron development; radial glia-guided pyramidal neuron migration; regulation of neurogenesis
Cellular component: extracellular exosome; endoplasmic reticulum; endoplasmic reticulum membrane
Genetic constraint (gnomAD): Loss-of-function variants: 18 observed, 45.05 expected, observed/expected ratio (o/e) 0.4, 90% interval 0.28 to 0.59. The upper end of that interval is the gene's LOEUF score, 0.59, which puts it in group 2 of 6, group 1 being the genes least tolerant of losing a copy. Missense variants: 254 observed, 404.89 expected, observed/expected ratio (o/e) 0.63, 90% interval 0.56 to 0.7. Synonymous variants: 121 observed, 144.1 expected, observed/expected ratio (o/e) 0.84, 90% interval 0.72 to 0.98.
Homologues: Orthologues: chimpanzee MEST (100% identical), pig MEST (99% identical), guinea pig MEST (99% identical), dog MEST (99% identical), rabbit MEST (99% identical), rat Mest (97% identical), mouse Mest (95% identical), zebrafish mest (73% identical), tropical clawed frog mest (71% identical), Caenorhabditis elegans Y73C8B.3 (13% identical), Caenorhabditis elegans C31H5.1 (12% identical), Drosophila melanogaster CG7632 (12% identical), and 10 more. Paralogues in human: ABHD11 (21% identical), ABHD5 (19% identical), EPHX2 (19% identical), EPHX4 (17% identical), ABHD14A (16% identical), ABHD4 (16% identical), EPHX3 (16% identical), ABHD6 (14% identical), ABHD8 (14% identical), BPHL (14% identical), SERHL2 (13% identical), ABHD14B (11% identical).
Diseases named in the same sentence as MEST in open-access papers:
MEST is named in the same sentence as 51 diseases in open-access papers, as found by Europe PMC text mining. Sharing a sentence is not in itself a finding about the gene and the disease. The quoted sentences say what the papers report.
Obesity (12 papers, 2006 to 2025). Accumulation of substantial excess body fat. "MEST expression has been previously associated with obesity in mice; however, a study in humans found MEST to possibly inhibit adipogenesis." (PMID 29988473, 2018). "MEST is a paternally imprinted gene that encodes a member of the α/β hydrolase fold family, and its expression has been described to be associated with obesity, adipocyte size, and preadipocyte proliferation in mouse and human studies." (PMID 29721103, 2018). "Since minimal additional physiological effects are observed in mice with inactivation of Mest, an intervention that represses the function of MEST, or its associated pathway, could be a feasible strategy to mitigate obesity and the inception of T2D." (PMID 28640866, 2017). "In addition, the high correlations between SFRP5, Naked1, and MEST in inguinal fat depots suggest a mechanism of coordinated regulation of the expression of these genes in association with susceptibility to diet-induced obesity." (PMID 16733553, 2006). "Since inactivation of Mest in mice has minimal additional effects aside from reduction of ATE, an intervention that mitigates MEST function in adipocytes is a plausible strategy to obviate obesity and type-2-diabetes." (PMID 28640866, 2017). "An important corollary to determining MEST function in adipose tissue expansion is that variation in diet-induced obesity in genetically identical adult mice could have developmental origins." (PMID 20574519, 2010). "These associations between gene expression and variable obesity phenotypes may merely indicate that the changes in expression of SFRP5, MEST, and other genes only result as a consequence of adiposity." (PMID 16733553, 2006). "In addition, Pip treatment can prevent obesity and improve lipid metabolism by regulating adipose tissue expansion (ATE) related genes Sfrp5, MEST, PTRF/Cavin1." (PMID 38547097, 2024). "The results indicate that SFRP5, MEST, and BMP3, but not Naked1, are positively associated with the subsequent development of diet-induced obesity in 16 wk-old mice." (PMID 16733553, 2006).
breast carcinoma (10 papers, 2013 to 2025). "This is because some genes, such as MEST LOI in breast cancer, appear to coincide with expression downregulation, casting doubt on the assumption that LOI invariably leads to increased gene expression." (PMID 39766305, 2024). "Ten pairs of tissue samples (breast cancer and normal) were randomly distributed for MS-PCR, and 8/10 (80%) of the breast cancer tissue samples had lower methylation levels of MEST promoter versus normal adjacent tissues." (PMID 30787268, 2019). "The good correlation between ZFP57 and MEST expression in tissues led us to further explore the possibility that ZFP57 regulates MEST expression in breast cancer cells." (PMID 30787268, 2019). "As shown by our results, expression levels of MEST were investigated in breast cancer tissues using mRNA qRT-PCR and Western blot; indeed, MEST was found to be significantly up-regulated in breast cancer tissues as compared with adjacent normal tissues." (PMID 30787268, 2019). "For example, miR-335 harbored within an intron of a protein-coding gene MEST, was known to be co-regulated with MEST by promoter hypermethylation in breast cancer cells, HCC and gastric cancer." (PMID 30785618, 2018). "The transcription of miR-335 was shown to be co-regulated with MEST by promoter hypermethylation in breast cancer cells." (PMID 23229728, 2013). "For example, MEST induces Twist-1-mediated EMT via STAT3 activation in breast cancers." (PMID 40830747, 2025). "Moreover, MEST expression has been demonstrated to be up-regulated in ovarian cancer tissues, and is also markedly up-regulated in breast cancer tissues where its inhibition can attenuate breast cancer cell proliferation." (PMID 34416900, 2021). "MEST expression levels in both breast cancer tissues and cell lines were detected." (PMID 30787268, 2019). "Moreover, the analysis using mRNA qRT-PCR and Western blot revealed that MEST expression was up-regulated in breast cancer cell lines when compared with HBL-100 cells." (PMID 30787268, 2019). "In summary, our study demonstrates that the ES-specific transcription factor ZFP57 is a tumour suppressor factor in breast cancer and targets oncogenic MEST directly through regulating the methylation of the MEST promoter region and subsequently suppressing the Wnt/β-catenin pathway." (PMID 30787268, 2019). "Besides this, the results suggested that elevated or reduced expression of ZFP57 can decrease or increase expression of MEST, respectively in breast cancer cells." (PMID 30787268, 2019). "Taken together, they illustrated that MEST may be the functional target of ZFP57 in breast cancer." (PMID 30787268, 2019). "In addition, miR-335 and its host gene, MEST, are silenced in association with CGI methylation in hepatocellular carcinoma (HCC), and replacement of miR-335 exerts tumor suppressive effects in lung, pancreatic and breast cancer cells, which is suggestive of the therapeutic potential of miR-335." (PMID 26214687, 2015). "For example, breast cancer frequently features LOI in genes such as IGF2, HM13, MEST and MEG3." (PMID 39766305, 2024). "Although some studies found that MEST can promote cancer metastasis in lung cancer and breast cancer, the role of MEST in ESCC has not been reported." (PMID 37149929, 2023). "With treatment of 5-AzaDc, MEST expression was strengthened in MCF-7 cells, which also supported our hypothesis that demethylation has a vital role in MEST overexpression in breast cancer cells." (PMID 30787268, 2019). "Moreover, analysis of MS-PCR appeared to show that the promoter region of the MEST was significantly hypomethylated in breast cancer tissues as opposed to normal adjacent tissues or, rather, MEST expression was regulated by ZFP57 through conserving its DNA methylation in breast cancer cells." (PMID 30787268, 2019).
hepatocellular carcinoma (6 papers, 2013 to 2026). A malignant tumor that arises from hepatocytes. "Intronic miR-335 is reported to be co-regulated with host gene MEST by promoter hypermethylation in hepatocellular carcinoma." (PMID 26610476, 2015). "Indeed, in hepatocellular carcinomas (HCC) the adenomatous polyposis coli (APC) and RASSF1 tumor suppressor genes were hypermethylated and the MEST gene was hypomethylated." (PMID 35215560, 2022).
infertile (6 papers, 2016 to 2024). "Intriguingly, gain of methylation at mICRs (e.g., KCNQ1OT1, MEST, PLAGL1 and SNRPN) and loss of methylation at pICRs (e.g., H19) are frequently observed in spermatozoa from infertile human patients." (PMID 27880848, 2016). "DNA methylation defects of three maternally imprinted genes, i.e., PLAGL1, MEST, and DIRAS3, have been identified in sperm DNAs from infertile males with a low semen concentration." (PMID 34368137, 2021). "The α1,3-fucosylation of MEST by FUT4 may serve as a new biomarker for evaluating the functional state of pregnancy, and a target for infertility treatment." (PMID 37798282, 2023).
male infertility (5 papers, 2019 to 2024). The inability of the male to effect fertilization of an ovum after a specified period of unprotected intercourse. "The imprinted gene MEST has been associated with male infertility as well as alterations in methylation of its ICR in both humans and mice." (PMID 36142363, 2022). "One of these genes, MEST, has been repeatedly found as hypermethylated in association with the male infertility phenotype." (PMID 34368137, 2021). "A recent meta-analysis has confirmed this association between male infertility and aberrant sperm DNA methylation, in particular for imprinted regions H19, MEST, and SNRPN." (PMID 31462300, 2019). "Importantly though, a number of studies have reported an association between male infertility and aberrant sperm DNA methylation for the genomic imprinted regions H19, MEST, and SNRPN." (PMID 31462300, 2019). "H19 and MEST were the most investigated genes in aberrant sperm samples, showing repetitively aberrant loss or gain of methylation, respectively, which, in turn, may be causal factors in the development of male infertility." (PMID 34368137, 2021). "Methylation anomalies of the H19, IGF2, GNAS, GNASAS, and MEST imprinted genes have not previously been associated with male infertility based on transcriptome data." (PMID 39017772, 2024). "We examined methylation of the ICRs of H19, MEST, KCNQ1OT1 and SNRPN, genes previously reported to be altered in male infertility and/or regions known to have roles in imprinting disorders." (PMID 36611168, 2023). "Particularly, DNA methylation defects of MEST and H19 within imprinted genes and MTHFR within non-imprinted genes have been repeatedly linked with male infertility." (PMID 34368137, 2021).
Silver-Russell syndrome (5 papers, 2013 to 2025). Silver-Russell syndrome is characterized by growth retardation with antenatal onset, characteristic facies and limb asymmetry. "MEST, located on chromosome 7q32, a gene belonging to a cluster of carboxypeptidase A (CPA) genes, has been implicated in postnatal and intrauterine growth restriction related to congenital Silver-Russell syndrome (SRS)." (PMID 37239377, 2023). "Diagnosed with Silver-Russell syndrome (SRS) using MS-MLPA, which revealed a normal copy number variant and hypermethylation of both GRB10 (7p12.1) and MEST (7q23.1) genes." (PMID 40730975, 2025). "In patients with Silver-Russell syndrome (SRS), one patient exhibited hypermethylation of the GRB10 and MEST genes, along with segmental uniparental disomy (UPD) on chromosome 7 (patient 1)." (PMID 40730975, 2025). "Methylation test for the two differentially methylated regions (DMRs) ICR1 and ICR2 regions at chromosome 11p15, the GRB10-PEG1/MEST loci at chromosome 7 and the DLK1-MEG3 locus at chromosome 14q32 were negative excluding main causes of Silver-Russell syndrome." (PMID 33952337, 2021).
lung carcinoma (4 papers, 2012 to 2024). "VCP is a multifunctional protein, and it has been shown to interact with MEST, promoting invasion and metastasis in lung cancer." (PMID 38495507, 2024). "MEST overexpression promoted metastasis of lung cancer cells in vivo and in vitro by activating NF-κB signaling." (PMID 34560900, 2021). "In this work, our immunohistochemical analysis of tumor tissue microarrays indicated that MEST is upregulated in lung cancer and its expression significantly correlates with lung cancer patient survival." (PMID 34560900, 2021). "Collectively, these results demonstrate that MEST plays an important role in driving invasion and metastasis of lung cancer by interacting with VCP to coordinate the IκBα/NF-κB pathway." (PMID 34560900, 2021). "We detected stronger MEST cytoplasmic staining in 68/90 (75.55%) lung cancer tissues as compared to corresponding normal tissues." (PMID 34560900, 2021). "We validated that MEST promotes lung cancer cell invasion and metastasis both in vitro and in vivo, and we confirmed that MEST is an important driver of lung cancer metastasis." (PMID 34560900, 2021). "In this regard, we proved that MEST indeed induces nuclear localization of p65, and upregulates p-p65 and p-IκBα to affect NF-κB signaling in lung cancer." (PMID 34560900, 2021). "In this study, we established two highly invasive lung cancer cell models (A549-i8 and H1299-i8) and identified mesoderm-specific transcript (MEST) as a novel invasive regulator of lung cancer." (PMID 34560900, 2021). "We report the discovery that MEST regulates lung cancer metastasis by activating the VCP/NF-κB/MMP2 signaling pathway." (PMID 34560900, 2021). "This study highlights the functional and clinical significance of MEST in lung cancer and the potential of MEST as a target for cancer therapeutics." (PMID 34560900, 2021). "Analysis of data from TCGA datasets indicated that MEST expression was frequently upregulated in tumor tissues compared with nontumor tissues in multiple cancer types, including esophageal, bladder, colon, liver, and lung cancers." (PMID 37149929, 2023). "Furthermore, high expressions of MEST and VCP were associated with poor survival of lung cancer patients." (PMID 34560900, 2021). "However, as its gene product, the role of MEST protein in lung cancer invasion and metastasis is unclear." (PMID 34560900, 2021). "By performing IP assay in lung cancer cells, we found that MEST bound to the C-terminal domain of VCP, suggesting that MEST may be a cofactor by binding to the C-terminal domain of VCP." (PMID 34560900, 2021). "Clinically, MEST is upregulated in lung cancer tissues, and high MEST expression significantly correlates with unfavorable clinicopathological features and with a shorter survival time of lung cancer patients." (PMID 34560900, 2021). "We measured the expressions of MEST and VCP by performing IHC of tissue microarrays containing 90 and 87 pairs of primary lung cancer tissues and adjacent normal tissues, respectively." (PMID 34560900, 2021). "MEST, DHX16 and RNPC7 were not only upregulated in highly invasive A549-i8 cells, but also highly expressed in lung cancer." (PMID 34560900, 2021). "Furthermore, analyzing the expression of MEST and VCP by using the Gene Expression Omnibus database, we found that the expression levels of these genes in lung cancer tissues were markedly higher than in normal tissues." (PMID 34560900, 2021). "The interaction between MEST and VCP was then confirmed by both immunoprecipitation and immunofluorescence staining analysis, showing that MEST co-localized with VCP in the perinuclear area of lung cancer cells." (PMID 34560900, 2021).
gastric cancer (3 papers, 2017 to 2025). A primary or metastatic malignant neoplasm involving the stomach. "Thus, we evaluated if the methylation of the promoter of the MEST gene could be detected in plasma as a useful approach to non-invasive assessment of gastric cancer." (PMID 29075357, 2017). "There are multiple known gene targets for miR-29c-3p, which include Mesoderm-specific transcript (MEST) and Secreted protein acidic and rich in cysteine (SPARC), which are known to be involved with colorectal and gastric cancer." (PMID 41465589, 2025). "Consistently, the expression of miR-335 and MEST are highly correlated in TCGA HCC (R = 0.88; FDR = 9.87e-05), breast (R = 0.78; FDR = 0) and gastric cancer (R = 0.79; FDR = 0), further validating of the co-regulation relationship between miR-335 and MEST is needed." (PMID 30785618, 2018).
gestational diabetes (3 papers, 2014 to 2017). Carbohydrate intolerance first diagnosed during pregnancy. "For example, previously we have shown that methylation of the mesoderm-specific transcript/paternally expressed gene 1 (MEST/PEG1) gene is slightly decreased in cord blood and placenta of children exposed to gestational diabetes mellitus." (PMID 28854270, 2017). "In another study, DNA methylation levels at the maternally imprinted MEST gene were significantly lower in placenta and cord blood of women with gestational diabetes (88 treated dietetically and 98 with insulin) than in those without gestational diabetes." (PMID 24664798, 2014).
ovarian carcinoma (3 papers, 2021 to 2023). A malignant neoplasm originating from the surface ovarian epithelium. "Additionally, an earlier study has revealed that MEST, whose promoter is markedly hypomethylated in resistant relative to sensitive xenografts, participates in ovarian cancer." (PMID 34416900, 2021). "In conclusion, the current study provides evidence indicating that NEAT1 can potentially promote the growth, migration, and invasion of ovarian cancer cells in vitro as well as tumor growth in vivo by competitively binding to let-7 g, promoting MEST expression and inhibiting ATGL expression." (PMID 34416900, 2021). "Cumulatively, the findings demonstrated that NEAT1 could promote malignant phenotypes of ovarian cancer cells by regulating the let-7 g/MEST/ATGL signaling axis." (PMID 34416900, 2021). "However, whether other miRNAs known to interact with NEAT1 in ovarian cancer can also target the MEST or ATGL genes requires further comprehensive investigations." (PMID 34416900, 2021). "However, the role of MEST in ovarian cancer warrants further exploration." (PMID 34416900, 2021). "NEAT1 can upregulate the expression of TJP3, MEST, and ROCK1 in ovarian cancer cell lines, subsequently promoting the progression of ovarian cancer." (PMID 36011001, 2022). "Multiple putative miRNA targets of NEAT1 and the downstream proteins have been proposed to contribute to the oncogenic roles of NEAT1 in ovarian cancer, such as the NEAT1/miR-1312/TJP3, NEAT1/miR-506, NEAT1/let-7 g/MEST/ATGL, NEAT1/miR‐382‐3p/ROCK1, and NEAT1/miR-365/FGF9 axes." (PMID 37986114, 2023).